FOXH1 (forkhead box H1)
Description:
Transcriptional activator. Recognizes and binds to the DNA sequence 5'-TGT[GT][GT]ATT-3'. Required for induction of the goosecoid (GSC) promoter by TGF-beta or activin signaling. Forms a transcriptionally active complex containing FOXH1/SMAD2/SMAD4 on a site on the GSC promoter called TARE (TGF-beta/activin response element).
Synonyms: Fast-1; FAST1
Tractability: No criterion of Open Targets' tractability assessment is met for any kind of drug.
Gene: Protein-coding gene on chromosome 8 (144,473,412 to 144,475,873, reverse strand). Ensembl gene ENSG00000160973.
Subcellular location: Nucleus
Pathways (Reactome):
Developmental Biology: Formation of axial mesoderm; Germ layer formation at gastrulation; Signaling by NODAL
Signal Transduction: Signaling by Activin
Gene Ontology:
Molecular function: bHLH transcription factor binding; co-SMAD binding; DNA binding; DNA-binding transcription factor activity; DNA-binding transcription factor binding; nuclear androgen receptor binding; protein binding; protein domain specific binding; R-SMAD binding; sequence-specific DNA binding; SMAD binding; transcription corepressor activity; cis-regulatory region sequence-specific DNA binding; DNA-binding transcription activator activity, RNA polymerase II-specific; DNA-binding transcription factor activity, RNA polymerase II-specific; transcription cis-regulatory region binding
Biological process: cellular response to cytokine stimulus; negative regulation of androgen receptor signaling pathway; positive regulation of DNA-templated transcription; positive regulation of transcription by RNA polymerase II; aorta morphogenesis; cardiac right ventricle morphogenesis; determination of left/right asymmetry in lateral mesoderm; heart looping; nodal signaling pathway; outflow tract morphogenesis; secondary heart field specification; transforming growth factor beta receptor signaling pathway; ventricular trabecula myocardium morphogenesis; hepatocyte differentiation; negative regulation of transcription by RNA polymerase II; regulation of DNA-templated transcription; regulation of transcription by RNA polymerase II
Cellular component: activin responsive factor complex; chromatin; nucleus; transcription regulator complex
Genetic constraint (gnomAD): Loss-of-function variants: 14 observed, 13.49 expected, observed/expected ratio (o/e) 1.04, 90% interval 0.68 to 1.61. The synonymous counts are far from expectation, so gnomAD's model fits this gene poorly and the ratio says little. Missense variants: 643 observed, 445.25 expected, observed/expected ratio (o/e) 1.44, 90% interval 1.35 to 1.54. Synonymous variants: 273 observed, 187.31 expected, observed/expected ratio (o/e) 1.46, 90% interval 1.32 to 1.61.
Gene-disease validity (ClinGen):
ClinGen rates the evidence that FOXH1 causes each of these diseases.
congenital heart disease (autosomal dominant): Limited. A heart disease that is present at birth.
Homologues: Orthologues: chimpanzee FOXH1 (99% identical), pig FOXH1 (82% identical), macaque FOXH1 (81% identical), guinea pig FOXH1 (81% identical), dog FOXH1 (81% identical), mouse Foxh1 (77% identical), rat Foxh1 (77% identical), tropical clawed frog foxh1 (40% identical), tropical clawed frog foxh1.2 (34% identical), zebrafish foxh1 (33% identical). Paralogues in human: FOXA2 (21% identical), FOXM1 (20% identical), FOXC1 (20% identical), FOXE3 (19% identical), FOXJ3 (19% identical), FOXA1 (19% identical), FOXC2 (19% identical), FOXD1 (19% identical), FOXF1 (18% identical), FOXK1 (18% identical), FOXL2 (18% identical), FOXO6 (18% identical), and 29 more.